BCL2 (BCL2 apoptosis regulator)
Diseases named in the same sentence as BCL2 in open-access papers (continued):
Sharing a sentence is not in itself a finding about the gene and the disease.
tumor (continued). "However, treating cells with anticancer drugs, such as doxorubicin elevated expression levels of BCL-2 in resistant tumor cells and causes the development of multiple chemotherapy resistance." (PMID 24637737, 2014). "The data suggested a possible association between the BMI1, BCL2 and Cyclin-D1 in tumor cells." (PMID 23671559, 2013). "Next, because Bcl-2 is occasionally associated with resistance to anti-tumor agents, and is often observed in human carcinomas, we compared the expression of Bax (pro-apoptotic) and Bcl-2 (anti-apoptotic) mRNAs, which are parts of the mitochondrial pathway, in the OSCC cells in the absence of CMA." (PMID 24278362, 2013). "BCL2 for its part is believed to increase cell survival in E-cadherin-deficient tumor cells." (PMID 24023670, 2013). "A putative explanation for this seemingly contradictory finding could be the tumor histological type, as BCL2 protein expression is significantly associated to undifferentiated NPC." (PMID 23777485, 2013). "Furthermore, the methylation of BCL2 was found to be associated with tumor invasion in peripheral pulmonary adenocarcinoma." (PMID 23599765, 2013). "Thus, Bcl-2 contributes to the stabilization of the mitochondrial membrane permeability, inhibition of ΔΨm loss and cytochrome c release and, at least in tumor cells, to the stimulation of oxidative phosphorylation." (PMID 22675634, 2012). "We have also shown that the CD44+/CD133+ tumorsphere-forming and tumor-initiating cells have high Bcl-2 and loss of miR-34 expression, indicating that miR-34 and its target Bcl-2 might be involved in cancer stem cells." (PMID 19714243, 2009). "Because bcl-2 blocks apoptosis in vitro, and thus contributes to malignant cell accumulation, its over-expression is expected to be associated with more aggressive tumor biology." (PMID 17430582, 2007). "Our findings reveal details of a role for BP1 in caspase-dependent and bcl-2-linked mechanisms of tumor cell survival, and suggest BP1 could serve as a marker for drug resistance and a therapeutic target." (PMID 17854498, 2007). "Bcl-2 was found to be significantly associated with radioresistant tumours (P=0.03)." (PMID 15928664, 2005). "However, combined treatment with AS Bcl-2 and various anticancer agents caused marked inhibition of tumor growth." (PMID 16280040, 2005). "Bcl-2 expression and loss of bax expression was seen in 31% of the radioresistant tumours." (PMID 15928664, 2005).
tumor (continued). "Various apoptosis-associated regulatory proteins, such as Bcl-2, Bax and Bcl-X, may contribute to the rate of apoptosis in neoplasia." (PMID 11720445, 2001). "This led us to use the Bcl-2/Bax heterodimer as a target for new compounds which may provide a therapy particularly suited to tumour cells for which resistance to conventional therapy is associated with elevated expression of Bcl-2." (PMID 11437412, 2001). "Although depth of tumour invasion and lymph node status were clearly associated with favourable outcome, no relation between survival rates and average values of either AIs or MIs, or immunoreactive scores for Bcl-2 and Bax was observed." (PMID 9020481, 1997). "Furthermore, in vitro studies of PCa cell lines (from androgen‐insensitive and androgen‐sensitive tumors) have shown that drug‐induced reductions in prostatic inflammation are associated with tumor apoptosis and death through specific mitochondrial pathways involving BCL‐2." (PMID 40344485, 2025). "On the other hand, the loss of Bcl-2 expression might indicate that the tumor shifted toward different pro-survival pathways associated with more aggressive behavior; on this account, Bcl-2 loss has been proposed as a possible marker of tumor aggressiveness." (PMID 35344084, 2023). "Moreover, the treatment with BCL2 inhibitors was shown to induce the activation of cDC1s detectable in circulation, both in mice and in patients, altogether underlining that BCL2 acts as a cDC1-specific immune checkpoint that restrains tumor immunosurveillance." (PMID 37907944, 2023). "Overall, E2 levels were significantly positively correlated with tumor enrichment in the hallmark estrogen response pathway (red bars) and with the expression of genes demonstrated to be transcriptionally regulated by ER (BCL2, IGF1R, GATA3, PIK3CA) and ligand-dependent ER (ESR1, XBP1, TFF1)." (PMID 36428742, 2022). "Cancer progression per se is not only dependent on uncontrolled tumor cell proliferation, but also on reduced susceptibility of the malignant cells to apoptosis, which is deregulated by various mechanisms including upregulation of anti-apoptotic proteins like BCL-2." (PMID 34063475, 2021). "Compared with 2D monolayer cells, the transcription level of the BCL2 encoding anti-apoptotic protein in 3D MTSs was 1.55 times and 3.09 times higher up-regulated before and after the 5-FU treatment, respectively, which contributed to the progression of tumor drug resistance." (PMID 38650282, 2021). "Notably, activation of AMPK-induced tumor cell survival is associated with Bcl-2." (PMID 34179090, 2021). "In addition, CHOP overexpression during ER stress causes down‐regulation of BCL2 in tumor cells." (PMID 32592208, 2020). "Therefore, researchers detected the expression of STAT3 phosphorylation and Snail in tumor cells interacted with TAMs and tumor-associated endothelial cells expressing or overexpressing B-cell lymphoma-2 (Bcl-2), which could promote the secretion of IL-6." (PMID 32161718, 2020). "However, the underlying mechanism of the effect of Bcl-2 overexpression in HDACi-tolerant tumor still remains unclear." (PMID 32692721, 2020).
tumor (continued). "The favorable prognostic value of Bcl-2 positivity was also significant in overall survival (HR = 0.58, 95%-CI: 0.37–0.90; p = 0.015) with the pathologic tumor size, pathologic nodal stage, distant metastasis, and tumor-associated inflammation as the covariates of the model." (PMID 30630524, 2019). "Administration of nimbolide after 8 weeks of DMBA painting arrested tumor growth associated with induction of apoptosis and inhibition of autophagy as evidenced by a significant increase in Bax and cleaved caspase-9 and -3 with downregulation of Bcl-2, Beclin, ATG5, and LC-3." (PMID 30352996, 2018). "Although the risk factors for cystic or tumour development are unknown, pericoronal radiolucencies wider than 2.5mm seem to dysregulate cell death and increase anti-apoptotic bcl-2 protein activity, which increases the likelihood of pathological changes arising in the follicle." (PMID 28809364, 2017). "Furthermore, 8h dose-dependently induced cancer cell apoptosis which is associated with mitochondrial depolarization in tumor cells by up-regulating Bax, down-regulating Bcl-2, in addition to activating levels of the caspase cascade in a concentration-dependent way." (PMID 27824091, 2016). "Furthermore, Msln stimulated PI3/Akt and MAPK/ERK signaling and inhibits pro-apoptotic factors such as Bad and Bax and causes the tumor cells to survive for longer periods, and at the same time promotes the expression of anti-apoptotic gene such as Bcl-2 and Mcl-1." (PMID 27626699, 2016). "The expression of the proliferative protein pHH3 together with the apoptotic marker cleaved caspase-3 may indicate an aggressive behaviour of PTC and loss of apoptosis inhibition by bcl-2 protein can further amplify the role of these proteins in tumor progression." (PMID 26863116, 2016). "In summary, the immunolabeling of the proliferative protein pHH3 together with the apoptotic marker cleaved caspase-3 may indicate an aggressive behaviour of PTC and loss of apoptosis inhibition by bcl-2 protein can further amplify the role of these proteins in tumor progression." (PMID 26863116, 2016). "Likewise, hepatocellular autophagy can play a tumor suppression role in chronic liver disease, and an impaired cellular autophagy response due to mutation in Beclin/Bcl-2 gene or inhibition of cellular apoptosis by HCV can lead to malignant transformation and hepatocellular carcinoma." (PMID 27223299, 2016). "Finally, mitochondrial APC has been associated with tumor survival by regulating Bcl2." (PMID 23844091, 2013). "We demonstrated an overall BCL-2 mRNA overexpression, as well as an increased AI-1 and AI-2 in the salivary tumours when compared to normal salivary glands, and in addition we found an association between increased tumour size and high cellular proliferation index." (PMID 22313995, 2012). "Although further experimental evidence is required to conclusively address this conundrum, it is conceivable that sustained survival linked to high Bcl-2 expression may reduce the selection pressure to acquire further genetic mutations associated with advanced tumor progression." (PMID 22431925, 2012). "Therefore, it could be hypothesized that high expression of bcl-2 prevents cell proliferation, suppresses tumor growth and thereby is associated with a lower grade and pT-stage in RCCs, as previously stated." (PMID 19222834, 2009).
tumor (continued). "Thus, γc down regulation and inhibition of Jak-3/Stat-5A signaling by PGE2 present in the tumor supernatant, as obtained here, may fail to support sustained Bcl-2 expression, leading to CD4+ T cells susceptibility towards apoptotic death." (PMID 19812686, 2009). "Therefore, bcl-2 expression appears to be associated with less aggressive tumor behavior." (PMID 19445705, 2009). "In this study, we hypothesized that p27 deficiency would cooperate with Bcl-2 in tumor formation." (PMID 18382684, 2008). "Thus Bcl-2 proto-ontogeny expression may be implicated in the development of resistance of tumors to therapeutic agents and may contribute to tumor growth and perhaps to ontogenesis by allowing the inappropriate survival of cells with DNA abnormalities." (PMID 15310398, 2004). "In tumor tissues, FSLE was associated with increased protein expression of cleaved caspase-3 and Bax, along with decreased Bcl-2 levels." (PMID 42193203, 2026). "Venetoclax is a first-in-class pro-apoptotic BCL-2 Homology-3 (BH3) mimetic that selectively antagonizes the anti-apoptotic BCL-2 protein, thereby rapidly inducing apoptosis in sensitive tumor cells." (PMID 41484790, 2026). "A Phase Ib clinical trial (NCT03751436) combining enzalutamide and BCL-2 inhibitor venetoclax demonstrated reduced circulating tumor cells in responding patients." (PMID 42067541, 2026). "As tumor cells frequently upregulate Bcl-2, inhibitors of CDK9 and CDK12/13 represent promising anticancer drugs." (PMID 42204137, 2026). "Beclin 1, a tumor suppressor that interacts with Bcl-2, Bax, BAK, Casp8, and Bcl-XL, and triggers apoptosis and induces autophagy, was significantly increased in 60H muscle compared to that in age-matched wild-type mice." (PMID 41507123, 2026). "In vivo, OF12-GEL significantly suppressed tumor growth in both DMBA-induced SCC rats and A431 xenograft mice, reducing tumor volume by and improving survival to 60%, and markedly downregulating BCL-2, Ki67, TNF-α, and ABCB1." (PMID 41705136, 2026). "We further confirmed a potent synergy between BV and BCL2 inhibitors in tumor cell lines, indicating a promising strategy to overcome resistance in CTCL." (PMID 41762706, 2026). "Only serum levels of C20 CER, C22 CERand C24 CER were found to positively correlate withthe BAX/BCL2 ratio in tumour tissues in patientsbefore undergoing nCRT." (PMID 40821650, 2025). "Chen and Zhang explored the effect of US waves combined with drug-loaded microbubbles on tumor cell death, demonstrating that this approach promotes apoptosis in cancer cells by regulating the expression of Bcl-2 and Bax." (PMID 40698351, 2025). "The expressionof BCL2, which is decreased in tumor hepatocytes, canbe suppressed by four proteins (CDK1, VDAC1, MMP9,CYC), the expression of which is increased in malignant hepatocytes compared with hepatocytes from healthy livertissue." (PMID 41541554, 2025). "While most normal tissues respond to IR through DNA repair or senescence, tumor cells frequently develop resistance by overexpressing anti-apoptotic proteins like Bcl-2 or downregulating pro-apoptotic factors such as Bax." (PMID 40699859, 2025). "VEN is an oral Bcl-2 inhibitor that targets the Bcl-2 protein to suppress the apoptosis resistance of tumor cells, thereby exerting its anti-tumor effects." (PMID 41398814, 2025). "Immunostaining showed that the tumor cells were positive for CD20 and BCL-2, and that a minor component of the tumor cells was undeniably BCL-6 positive." (PMID 40772219, 2025).
tumor (continued). "Aggressively proliferating cancer cells overexpress Bcl-2, leading to mitochondrial resistance to apoptosis which underpins tumour persistence and therapeutic resistance." (PMID 41586225, 2025). "M2 macrophages led to the overexpression of numerous genes linked to tumor growth, angiogenesis, invasion, and immune suppression in NSCLC cells, increasing the BCL2/BAX ratio and promoting cellular resistance to apoptosis." (PMID 40076874, 2025). "sNK cells have shown enhanced survival in the tumor microenvironment (TME) due to elevated levels of anti-apoptotic proteins like BCL2 and reduced levels of pro-apoptotic proteins, enabling them to resist tumor-induced cell death." (PMID 40805135, 2025). "In tumor cells and HGSOC cells, overexpression of the anti-apoptotic protein Bcl-2 can inhibit apoptotic signals, thereby enhancing tumor cell resistance to chemotherapeutic agents." (PMID 40370464, 2025). "We report two potent DNAzymes, DNZ-15 and DNZ-35a, which downregulate BCL-2 expression in cancer cell lines and suppress tumor growth in a murine cancer model, thus providing a foundation for future DNAzyme-based cancer therapeutics." (PMID 40643466, 2025). "In TNBC cells and patient tumours, we observed that immunofluorescence staining of BCL2 overlapped with RASAL2, suggesting subcellular co-localisation of the two proteins." (PMID 39890967, 2025). "Secondly, bioactive components in dandelion induce tumor cell apoptosis through the mitochondrial Bcl-2/caspase pathway." (PMID 41374059, 2025). "The anti-apoptotic BCL2 protein is involved in apoptosis resistance and tumor cell invasion/migration." (PMID 39970625, 2025). "Bcl-2, an anti-apoptotic protein that prolongs cell survival by inhibiting apoptosis, thereby promotes tumor development and treatment resistance." (PMID 40750570, 2025). "Dysregulation of NF-κB promotes tumor growth, survival, and resistance to therapy by upregulating anti-apoptotic genes such as Bcl-2, Bcl-xL, and XIAP, thereby inhibiting apoptosis 21-25." (PMID 40765826, 2025). "LncRNA MALAT1 and HOTAIR are highly expressed in LUAD, promoting tumor cell proliferation, and inhibiting apoptosis by regulating cell cycle proteins and apoptosis-related molecules (such as BCL-2 and BAX)." (PMID 39834603, 2025). "It enhances the cleaved expression of Caspase-9, reduces the production of bcl-2, induces tumor cell apoptosis, and decreases the expression of vascular endothelial growth factor to reduce tumor angiogenesis." (PMID 40584613, 2025). "Transfection with sh-TLK1#1 markedly increased the apoptosis rate and Bax protein levels while decreasing Bcl-2 expression in tumor cells." (PMID 40369698, 2025). "The MAPK pathway resists apoptosis by regulating cell survival-related proteins such as Bcl-2, thereby enhancing tumor cell survival." (PMID 39940440, 2025). "Enhancing the sensitivity of tumor cells to apoptosis by treatment with BCL2 inhibitors, such as ABT737, or other apoptosis inducers can effectively overcome EGFR-TKI resistance." (PMID 41281943, 2025).